CD93 (CD93 molecule)
Diseases named in the same sentence as CD93 in open-access papers (continued):
Sharing a sentence is not in itself a finding about the gene and the disease.
age-related macular degeneration (2 papers, 2023 to 2025). Age-related loss of vision in the central portion of the retina (macula), secondary to retinal degeneration. "Altered CD93 expression has been detected in the choroidal ECs of patients with age-related macular degeneration and pre-eclampsia." (PMID 40943530, 2025). "CD93 is mainly expressed on endothelial cells, where it plays a key role in promoting angiogenesis both in physiology and disease, such as age-related macular degeneration and tumor angiogenesis." (PMID 37443812, 2023). "We also showed an involvement of CD93 in age-related macular degeneration (AMD), with it being highly expressed in the choroidal endothelial cells of these patients." (PMID 37443812, 2023). "The aim of this review is to provide an overview of the current literature regarding the multifaceted role of CD93 in efferocytosis and angiogenesis, but also in pathological conditions such as tumors, age-related macular degeneration (AMD) and inflammatory diseases." (PMID 37443812, 2023).
allergic asthma (2 papers, 2020 to 2025). A asthma with a basis in a pathological type I hypersensitivity reaction. "We demonstrated that allergic asthma is associated with significant changes in CD93 expression and serum levels in both in vitro and in vivo models." (PMID 31941986, 2020). "However, in allergic asthma, the potential roles of soluble CD93 (sCD93) have not been well studied." (PMID 31941986, 2020).
autoimmune disorders (2 papers, 2020 to 2025). "Transcriptome group 3 (ACVRL1, CD93, CEBPB, NINJ1, SRGN) encodes preferentially for proteins related to autoimmunity." (PMID 32325790, 2020).
breast carcinoma (2 papers, 2019 to 2025). "Silencing CD93 and MMRN2 inhibited integrin β1 activation, suppressing the PI3K/AKT/SP2 signaling pathway and reducing breast cancer growth and VM." (PMID 40943530, 2025).
cholangiocarcinoma (2 papers, 2023 to 2025). A carcinoma that arises from the intrahepatic biliary tree (intrahepatic cholangiocarcinoma) or from the junction, or adjacent to the junction, of the right and left hepatic ducts (hilar cholangiocarcinoma). "Notably, CD4+ on activated regulatory T cells expressing CD39 were found to mediate 12.384% of the increased cholangiocarcinoma risk associated with CD93." (PMID 40943530, 2025).
colitis (2 papers, 2019 to 2024). Inflammation of the colon. "DR3-driven loss of ILC3s in the large intestine is an essential factor contributing to the exacerbation of colitis, and mice lacking CD93 expression in ILC3s also exhibit impaired IL-22 production and increased colonic inflammation." (PMID 39162488, 2024).
heart failure (2 papers, 2023 to 2025). Inability of the heart to pump blood at an adequate rate to meet tissue metabolic requirements. "In fact, they found that higher plasma concentrations of the CD93 gene’s polymorphism rs2749812 were associated with higher concentrations of N-terminal pro-B-type natriuretic peptide (NT-proBNP), a marker of the severity of heart failure-associated congestion." (PMID 37371490, 2023). "Although further studies are needed to definitely assess the role of CD93 in heart failure, current evidence suggests that this protein may also represent a molecular target in this cardiovascular disease." (PMID 37371490, 2023).
hepatocellular carcinoma (2 papers, 2025). A malignant tumor that arises from hepatocytes. "In vitro and in vivo experiments support that miR-99a-5p negatively regulates alternative polarization of macrophages, decreases collagen deposition in chronic liver injury model, and suppresses the progression of hepatoma in a xenograft model partially by targeting CD93." (PMID 40211350, 2025).
inflammatory skin disease (2 papers, 2022 to 2026). Inflammatory skin disorders covers a broad category that includes many conditions ranging in severity, from mild itching to grave medical health complications These disorders are common in people of all ages and races. "Similarly, in inflammatory skin diseases, IL-17D regulates keratinocyte-mediated inflammatory responses through the CD93‒p38 MAPK‒protein kinase B (AKT)-Smad2/3 signaling axis." (PMID 40536951, 2026).
ischemic stroke (2 papers, 2023 to 2025). A stroke disorder caused by obstruction of blood flow to the brain, due to thrombotic (local blood clot formation) or embolic (due to a blood clot or other material traveling from another site) event. "Recent research has identified CD93 as a promising therapeutic target for evaluating functional outcomes after ischemic stroke." (PMID 40943530, 2025). "In a study of 33 ischemic stroke patients, CD93 transcript levels were found to be double those of to the control group." (PMID 40943530, 2025). "In a small cross-sectional case-control study on 33 individuals with ischemic stroke and matched controls, the CD93 transcript was 2-times higher in patients who suffered from ischemic stroke." (PMID 37371490, 2023).
lupus (2 papers, 2021 to 2025). "Apoptotic cells are considered a source of autoantigens in lupus, and the receptor CD93 can effectively opsonize these cells." (PMID 40943530, 2025). "Among the surface molecules, the expression of CD55, CD86, CD93, and CCR6 were decreased in G-MDSCs from pristane-induce lupus mice, and INK128 could increase the expression of these genes." (PMID 34282122, 2021).
periodontitis (2 papers, 2024 to 2025). An acute or chronic inflammatory process that affects the tissues that surround and support the teeth. "Among these, CD93 emerged as a key gene, validated for its significant association with periodontitis." (PMID 40943530, 2025). "Our MR analysis, using eQTL and pQTL data, identified significant causal relationships between periodontitis and the genes CD93, CD69, and CXCL6." (PMID 39717623, 2024). "The results showed significant causal relationships between CD93, CD69, and CXCL6 and periodontitis." (PMID 39717623, 2024). "The findings suggest that CD93, CD69, and CXCL6 are closely related to the progression of periodontitis, with MR confirming their causal links to the disease." (PMID 39717623, 2024). "Our findings enhance personalized medicine strategies for periodontitis by identifying key biomarkers CD93, CD69, and CXCL6 and their links to the disease through MR." (PMID 39717623, 2024). "CD93 is critical in regulating immune cell adhesion and migration, key processes in the inflammatory response of periodontitis." (PMID 39717623, 2024). "The results showed that CD93, CD69, and CXCL6 were all significantly causally associated with the occurrence of periodontitis." (PMID 39717623, 2024). "Additionally, to further explore the specific roles of these key genes in the pathological process of periodontitis, we analyzed the cell-type-specific expression patterns of CD93, CD69, and CXCL6 using single-cell RNA sequencing." (PMID 39717623, 2024). "MR confirmed significant causal relationships between CD93, CD69, and CXCL6 and periodontitis." (PMID 39717623, 2024). "To explore the connections between CD93, CD69, and CXCL6 and periodontitis, we performed single-cell data analysis." (PMID 39717623, 2024). "We conducted a detailed analysis of the expression levels of CD93, CD69, and CXCL6 in normal and periodontitis tissues, revealing that all three genes were significantly upregulated in periodontitis tissues." (PMID 39717623, 2024). "This suggests that CD93, CD69, and CXCL6 are not only involved in the immune responses driving periodontitis but may also serve as promising therapeutic targets." (PMID 39717623, 2024).
preeclampsia (2 papers, 2024 to 2025). Preeclampsia is a hypertensive disorder of pregnancy that is characterized by new-onset hypertension with proteinuria presenting after 20 weeks of gestation, and depending on mild or severe forms may initially present with severe headache, visual disturbances, and hyperreflexia. "In addition to the circulating complement component alteration during preeclampsia, the cell surface component, such as CD93 (C1qRp or C1qR1 expressed on endothelial cells), level decreases in the circulation, whereas its level increases in the serum during the first trimester of normal pregnancy." (PMID 40904461, 2025).
active tuberculosis (1 paper, 2025). "Interestingly, the expression of CD93 has been associated with active tuberculosis (TB) and polycystic ovary syndrome (PCOS)." (PMID 40943530, 2025).
Alzheimer disease (1 paper, 2022). A progressive, neurodegenerative disease characterized by loss of function and death of nerve cells in several areas of the brain leading to loss of cognitive function such as memory and language. "In AlzData database, the levels of CD44, CD93, and CD163 in patients with Alzheimer’s disease (AD) were significantly increased than those in normal controls." (PMID 35356296, 2022).
aneurysmal diseases (1 paper, 2021). "However, no research has focused on the mechanism of action of CD93 molecules in aneurysmal diseases." (PMID 33531038, 2021).
chronic lymphocytic leukaemia (1 paper, 2008). "EST accession [GenBank:AI380234] hit CD93 that is from a B-cell, chronic lymphocytic leukaemia flow-sorted cell line (NCI_CGAP_CLL1), while vWF hit a non-endothelial EST from the NCI_CGAP_Br4 library [GenBank:AA721546]." (PMID 18394197, 2008).
experimental autoimmune encephalomyelitis (1 paper, 2022). An autoimmune demyelinating disease of the central nervous system that is produced experimentally in animals by the injection of homogenized brain or spinal cord in Freund's adjuvant. "For experimental autoimmune encephalomyelitis mice, these infiltrating microglial cells or monocytes with overexpressed CD93 tend to cause T cells apoptosis, which greatly immunosuppressed functional CD4+ and CD8+ T cells." (PMID 36006582, 2022).
gastritis (1 paper, 2024). Inflammation of the stomach. "Second, since all samples were collected after surgery, the expression of CD93 has not been determined in gastric biopsy tissues of premalignant lesions, such as gastritis and intestinal metaplasia." (PMID 39190192, 2024).
head and neck cancer (1 paper, 2019). A primary or metastatic malignant neoplasm affecting the head and neck. "CD93 has been described as a key gene in a proposed ‘tumour angiogenesis signature’ determined by meta‐analysis of 959 breast cancers, 170 renal cancers and 121 head and neck cancers." (PMID 31287944, 2019). "Similar to CD93, CLEC14A was described as a key gene in a proposed ‘tumour angiogenesis signature’ determined by meta‐analysis of over 1000 tumour samples including breast, renal and head and neck cancers." (PMID 31287944, 2019).
hyperglycaemia (1 paper, 2023). "Finally, hyperglycaemia induced an impairment in the stress-induced release of CD93." (PMID 37371490, 2023).
Immunodeficiency (1 paper, 2022). Failure of the immune system to protect the body adequately from infection, due to the absence or insufficiency of some component process or substance. "Our data indicated that the top three positively enriched KEGG, from a pan-cancer perspective, in the elevated expression of CD93 were cytokine–cytokine/immunodeficiency." (PMID 35242761, 2022).
kidney inflammation (1 paper, 2025). "By investigating multiple inflammatory mediators (CD93, CD36, STAT3, NF-Kappa B, and TLR2/4), our results highlight the therapeutic potential of hAAT in treating kidney inflammation." (PMID 40723823, 2025).
Lewis lung carcinoma (1 paper, 2024). "To assess whether CD93 deficiency also affects vascular integrity in other metastatic tumors, we implanted Lewis lung carcinoma cells (LLC1) subcutaneously in wild-type and CD93-deficient mice." (PMID 38441970, 2024).
Lymphadenopathy (1 paper, 2013). Enlargement (swelling) of a lymph node. "B220+, CD19+ and CD93+, but not c-kit+ splenocytes isolated from an HIV Tg mouse in the last stage of splenomegaly and lymphadenopathy induced tumors in NOD/SCID mice." (PMID 23985023, 2013).
metastatic cancers (1 paper, 2024). A carcinoma which has spread from the original site of growth to another anatomic site. "CD93 has emerged as a target for antiangiogenic therapy, but its importance for vascular integrity in metastatic cancers has not been evaluated." (PMID 38441970, 2024).
metastatic tumors (1 paper, 2024). "CD93, MMRN2, and fibronectin are coexpressed in the vasculature of primary metastatic tumors and metastatic lesions." (PMID 38441970, 2024).
multiple myeloma (1 paper, 2015). "In an American study, high expression of CD93 was associated with higher survival rate among patients with multiple myeloma (MM) treated with bortezomib, indicating that high levels of CD93 may be a possible marker for better outcome in these patients." (PMID 26008729, 2015).
non-small cell lung carcinoma (1 paper, 2022). A group of at least three distinct histological types of lung cancer, including non-small cell squamous cell carcinoma, adenocarcinoma, and large cell carcinoma. "Noninvasive 125I-anti-CD93 mAb radioimmunoimaging may be used for the early diagnosis and therapy delamination of non-small cell lung cancer." (PMID 36006582, 2022).
osteosarcoma (1 paper, 2025). A usually aggressive malignant bone-forming mesenchymal neoplasm, predominantly affecting adolescents and young adults. "The CD93 gene exacerbated cell proliferation, angiogenesis, and immune evasion in osteosarcoma by triggering the PI3K/AKT pathway." (PMID 40344088, 2025).
periodontal disease (1 paper, 2024). "Beyond its well-documented roles, CD93 also influences the maturation and differentiation of immune cells, potentially modulating the immune landscape in periodontal disease." (PMID 39717623, 2024).
pleural mesothelioma (1 paper, 2024). A neoplasm that arises from the mesothelial cells of the pleura. "To elucidate whether CD93 of human MCs also regulates antitumor immunity in lung tumor patients, we first confirmed that NCI-H2452 human pleural mesothelioma cells also expressed higher levels of Cd93 and Ccl21 mRNA than human umbilical vein endothelial cells (HUVECs)." (PMID 38250037, 2024).
Splenomegaly (1 paper, 2013). Abnormal increased size of the spleen. "Staining for precursor B cell markers revealed that the majority of B cell populations circulating in peripheral blood as well in bone marrow and spleen during the last stages of splenomegaly consisted of B220+CD19+CD43+CD93+CD127+ precursor B cells." (PMID 23985023, 2013).
Stroke (1 paper, 2023). Sudden impairment of blood flow to a part of the brain due to occlusion or rupture of an artery to the brain. "As previously observed for other clinical conditions, the association between CD93 and stroke needs to be validated in future longitudinal controlled studies that are adequately powered to define the prognostic role of CD93 in stroke." (PMID 37371490, 2023).
ulcerative colitis (1 paper, 2025). An inflammatory bowel disease involving the mucosal surface of the large intestine and rectum. "Through the establishment of ulcerative colitis animal models combined with RNA-seq and ASTRAL-DIA proteomic analyses, we validated that specific hub genes, including Anxa1, Cd93, and Mfge8, exhibited consistent alterations at both the transcriptional and protein levels." (PMID 41050686, 2025).
tumor (65 papers, 2015 to 2026). "CD93 deficiency destabilizes blood vessels in primary tumors, facilitates tumor cell invasion into the vasculature, and promotes a conducive microenvironment at metastatic sites." (PMID 40943530, 2025). "Elevated CD93 levels were associated with tumor angiogenesis, immune cell infiltration, poor prognosis, and advanced TNM stages." (PMID 40943530, 2025). "The upregulation of CD93 on tumor-associated ECs and the promising results from blocking CD93 signaling have catalyzed numerous preclinical and clinical trials." (PMID 40943530, 2025). "Another study analyzing RNA-seq data from 22 patients with esophagogastric junction adenocarcinoma(AEG) suggests that CD93 functions as an oncogene with its expression linked to T-stage and maximum tumor diameter." (PMID 40943530, 2025). "Gene set enrichment analysis (GSEA) in COAD, BLCA, KIRC, and LIHC showed that the high CD93 expression group was enriched in gene sets related to cell migration and tissue migration pathways, which are closely associated with tumor angiogenesis." (PMID 40943530, 2025). "CD93 plays a role in tumor-associated vasculature, and changes in Col1a2 expression have been observed after radiotherapy in other cancers." (PMID 40244686, 2025). "Biomarker correlation analysis across 25 immunotherapy cohorts revealed that in 8 cohorts, CD93 had the same predictive value as tumor mutation burden (TMB), a finding corroborated by a pan-cancer analysis." (PMID 40943530, 2025). "Multiple studies have demonstrated that CD93 is significantly overexpressed in tumor-associated vasculature and is associated with tumor malignancy, progression, metastasis, and immune infiltration." (PMID 40943530, 2025). "CD93 expression was associated with tumor location and microsatellite instability, and high CD93 levels were linked to improved overall survival." (PMID 40943530, 2025). "Conversely, treating tumor-bearing mice with a neutralizing antibody against CD93 that blocks its interaction with IGFBP7 was associated with vascular normalization." (PMID 38441970, 2024). "In line with a hyperresponsiveness to VEGF, we observed a substantial increase in MMP9 levels in CD93-deficient subcutaneous tumors and lung metastases, which was associated with enhanced invasion and improved colonization of tumor cells." (PMID 38441970, 2024). "Recent studies have shown CD93 to be intensely upregulated on tumor-associated endothelium, supported by its status as one of the top 20 genes associated with human primary tumor angiogenesis signature surveying head and neck, breast, kidney, and brain tumors." (PMID 38468017, 2024). "Studies have shown that tumor development in CD93 knockout mice or loss of CD93 in endothelial cells were associated with disruption of endothelial junctions and increased vascular permeability." (PMID 39045455, 2024). "Nevertheless, our data suggest that the increased responsiveness of tumor endothelial cells to VEGF underlies the high MMP9 expression in CD93-deficient tumors." (PMID 38441970, 2024). "Here, we demonstrate that CD93 deficiency destabilizes the primary tumor vasculature, facilitating the intravasation of tumor cells, and creates a permissive microenvironment at the metastatic site." (PMID 38441970, 2024). "CD93 has emerged as a potential target for antiangiogenic therapy, owing to its association with tumor angiogenesis in human cancers." (PMID 38441970, 2024). "Since this protein family has been linked to tumor development (especially CD93, CLEC14A and CD248), there is a great interest in studying these proteins as possible therapeutic targets in cancer treatment." (PMID 37443812, 2023).